Y_RNA (Y RNA )
Gene: Miscellaneous RNA gene on chromosome X (96,701,507 to 96,701,619, reverse strand). Ensembl gene ENSG00000207426.
Homologues: Orthologues: chimpanzee Y_RNA (100% identical), macaque Y_RNA (95% identical). Paralogues in human: RNY1 (92% identical), Y_RNA (91% identical), Y_RNA (90% identical), Y_RNA (89% identical), Y_RNA (88% identical), RNY1P11 (88% identical), RNY1P8 (87% identical), Y_RNA (87% identical), RNY1P7 (86% identical), Y_RNA (86% identical), Y_RNA (85% identical), Y_RNA (84% identical), and 99 more.